BGN (biglycan)
Diseases named in the same sentence as BGN in open-access papers (continued):
Sharing a sentence is not in itself a finding about the gene and the disease.
tumor (continued). "Although biglycan was hardly expressed in normal blood vessels, it was strongly expressed in tumour blood vessels." (PMID 22374465, 2012). "Many cancer cells such as A375SM cells, which were used to create the tumour xenografts that were the source of TECs in this study, were reported to express a low level of biglycan." (PMID 22374465, 2012). "In this study, we detected the specific expression of biglycan in TECs isolated from xenografted tumours in mouse and human clinical cancers." (PMID 22374465, 2012). "Therefore, while BGN directly enhances tumor cell aggressiveness, its impact on immune suppression appears to be a major driver of tumor progression in vivo." (PMID 41328346, 2026). "Both paired and independent analyses confirmed a significant upregulation of BGN in tumor tissues." (PMID 41328346, 2026). "In conclusion, our study not only reveals a novel enhancer-mediated transcriptional mechanism involving NR2F2 and BRD4 that activates BGN in PTC but also highlights BGN's dual role in promoting tumor cell-intrinsic aggressiveness and shaping the tumor immune environment." (PMID 41328346, 2026). "Additionally, immunohistochemical (IHC) staining of formalin-fixed paraffin-embedded (FFPE) samples from 71 PTC patients (including 20 paired samples) revealed significantly stronger BGN staining in tumor tissues." (PMID 41328346, 2026). "Importantly, patients with high BGN expression in tumor cells or fibroblasts exhibited significantly poorer prognosis, while high BGN expression in endothelial or smooth muscle cells correlated with better survival." (PMID 41328346, 2026). "And the tumor promotion effect of CAFs may be executed by BGN/MDK axis, which also reduced CD8+ T cell infiltration in TME." (PMID 41833003, 2026). "We applied a biglycan/BGN antibody to stain 70 samples with accessible tumor sections from the current transcriptome analysis cohort (screening set) and 56 samples from an independent molecularly diagnosed ST-EPN ZFTA-RELA cohort applied in previous studies (validation set)." (PMID 39762990, 2025). "As epigenetic dysregulation of another biomarker, biglycan, appears to promote tumor metastasis, future studies should investigate whether LOX-1 upregulation occurs via a similar mechanism." (PMID 40563926, 2025). "BGN has been shown to enhance tumor malignancy via activation of the NF-κB signaling pathway." (PMID 41465449, 2025). "Moreover, in vivo xenograft assays of co-injected DU145 cells and CAFs showed that BGN expressed by CAFs positively regulates tumor growth in BALB/c nude mice." (PMID 41470114, 2025). "Also, Biglycan can promote tumor angiogenesis through multiple mechanisms, including facilitating endothelial cell motility and stimulating the release of growth factors." (PMID 39155517, 2025). "This broad expression pattern raises the possibility that BGN could serve as a therapeutic target for CAFs across the ESCC tumor microenvironment." (PMID 41465449, 2025). "However, the expression of biglycan by CAFs was associated with a lower presence of CD8+ T cells, thus creating an immunosuppressive tumoural environment in the TNBC/basal-like subtype." (PMID 41463344, 2025). "Biglycan expression on the surface of tumor endothelial cells (TECs) has high LDL affinity." (PMID 40563926, 2025). "Additionally, mouse models were established using human Skov3 cells, which cannot reflect the impact of the tumor microenvironment on PDK1 or BGN during EOC progression." (PMID 39578715, 2024). "Notably, the expression levels of APOE, BGN, C1QB, and BST2 were found to correlate with cancer genomic atlas data, and were implicated in tumor immune infiltration." (PMID 39650066, 2024). "In addition, biglycan is highly expressed in cancer, enabling tumor growth, invasion, and metastasis." (PMID 39334952, 2024).
tumor (continued). "Subsequently, leveraging the surface high markers of BGN + Fib and utilizing a deconvolution algorithm, we estimated the infiltration level of BGN + Fib in bulk sequencing data from the TCGA-CRC cohort, revealing a notable increase in BGN + Fib infiltration in tumor tissues." (PMID 38654221, 2024). "Furthermore, tumor-bearing mouse models are established to assess the impacts of PDK1 and BGN on EOC tumor growth and metastasisin vivo." (PMID 39578715, 2024). "Importantly, knocking out circ-BGN restores chemosensitivity to tumor cells, a process that is mediated by erastin-induced ferroptosis." (PMID 39759144, 2024). "Compared to the normal group, BGN was highly expressed in the tumor group." (PMID 38654221, 2024). "Indeed, a number of proteins within the PG score, such as LUM, HSPG2, DCN and BGN, have established tumor suppression functions in other cancer types." (PMID 38810090, 2024). "In a recent study, glycan-associated proteins such as CD147, BGN, VCAN, and TNC were found to be enriched in tumor EVs compared to EVs secreting from non-tumor adjacent tissues, which can be potentially used as cancer EV biomarkers or even to identify the cancer origin." (PMID 37773167, 2023). "In addition, TECs can accelerate lung metastasis of tumour cells with low metastatic potential by releasing the vascular secretory factor biglycan." (PMID 37389120, 2023). "Taken together, the results indicated that co-injection of anti-BGN HGC27+CAFLCs/sh-control rescued the inhibitory effect of knockdown BGN expression on subcutaneous tumor growth or intraperitoneal tumor dissemination, while co-injection of anti-BGN HGC27+CAFLCs/sh-FAP eliminated the rescued effect." (PMID 36632455, 2023). "We observed a delayed tumor growth in mice with BGN-expressing tumors as compared to the control." (PMID 37456245, 2023). "Although decorin acts as a tumor suppressor and biglycan is regarded as an oncogene, asporin exerts tumor-suppressor function in triple-negative breast cancer but exerts tumor-promotor function in some types of cancer, including breast, pancreatic, colorectal, gastric, and prostate cancer." (PMID 35600399, 2022). "Multiple HSPGs and CSPGs core proteins and related enzymes were upregulated in GBM tumors relative to normal brain, including various genes previously implicated in tumor invasion and tumorigenesis and observed by the present study, including glypican 1, CSPG4, BGN, and AGRN." (PMID 35202840, 2022). "Interestingly, endothelial cells in TME can also affect tumor cells by secreting angiocrine factors, such as biglycan, then promoting tumor cells metastasize." (PMID 36467048, 2022). "Existing studies have demonstrated the role of BGN in tumor proliferation, adhesion and invasion." (PMID 35154268, 2022). "Results showed an increase in COL10A1 protein in tumor tissue, and in BGN and FAP proteins involved in collagen fibril assembly and matrix degradation, respectively, emphasizing that these hub genes could have a crucial function in gastric tumorigenesis." (PMID 35328635, 2022). "Genes associated with tumor proliferation such as DSG2 and SPRR3 and genes related to energy metabolism process decreased along the invasion trajectory of the tumor, while the function of tumor progression-related gene BGN and metastasis growth-related gene POSTN gradually increased." (PMID 35899203, 2022). "BGN is a factor that participates in the integrated pathway of TGFβ/Snail with TNFα/NF-κB, which may facilitate tumor–stroma cross-talk during EMT in colorectal cancer." (PMID 36358747, 2022). "Furthermore, biglycan downregulates the expression of the tumor-suppressor gene, PTEN (p ≤ 0.01), and increases the expression of endothelial–mesenchymal transition (EMT) and aggressiveness markers vimentin (p ≤ 0.01) and fibronectin (p ≤ 0.01) in MG63 cells." (PMID 35267503, 2022). "Tumor endothelial cells may provide activation signals or secrete biglycan to stimulate cancer cell metastasis." (PMID 35061208, 2022).
tumor (continued). "Similarly, the comparison of 27 tumor tissues in TCGA with the corresponding para-cancer tissues also showed significant expression of BGN in tumor tissues." (PMID 35154268, 2022). "Therefore, BGN is closely related to the occurrence and development of a variety of tumors and is a potential target molecule for tumor treatment." (PMID 36110576, 2022). "In addition, biglycan has previously been shown to negatively affect tumor cell therapy response in OS and other tumors." (PMID 35267503, 2022). "However, few reports are available on the correlation between BGN expression in the tumor microenvironment and cancer progression." (PMID 33709550, 2021). "Furthermore, TECs attract tumor cells by secreting biglycan, which induces intravasation, followed by distant metastasis." (PMID 34069554, 2021). "Moreover, CCL2 and CCL5, whose expression is regulated in a biglycan-dependent manner, are known contributors that promote immune cells infiltration at the tumor site, metastasis, and angiogenesis." (PMID 34917515, 2021). "Since biglycan activates fibroblasts, inducing tumor stiffness and facilitating tumor cell invasion, its interactions with IGF-signaling could present a plausible cancer therapy target." (PMID 34069554, 2021). "Similarly, overall survival was significantly lower in cases with high BGN expression in the tumor (p = 0.0024)." (PMID 33709550, 2021). "In our immunohistochemical analyses conducted on tissues from CRC patients, high levels of biglycan expression were detected in the stroma around the CRC tissue, which is supportive of the critical role that increased biglycan expression plays in the ECM contributing to tumor progression." (PMID 35008869, 2021). "Our results suggest that biglycan destabilizes tumor blood vessels by mediating Angpt2 expression." (PMID 33966638, 2021). "However, biglycan itself indirectly induced Angpt 2 expression in endothelial cells; we propose that TNF-α stimulates tumor angiogenesis via suppression of vascular integrity and increased perfusion as a result of biglycan signaling." (PMID 33966638, 2021). "BGN may also promote tumor growth and chemotherapeutic resistance through the activation of NFκB signalling to maintain stem-like tumor cells as was shown in colon cancer." (PMID 34449016, 2021). "BGN is an essential constituent of the extracellular matrix (ECM) that exhibited an association with several human carcinomas, including GC, esophageal squamous cell carcinoma, pancreatic carcinoma, colon carcinoma, and neoplasms in blood vessels." (PMID 34868341, 2021). "Biglycan has bidirectional roles modulating tumor growth and progression in different tumor types." (PMID 33966638, 2021). "Biglycan expression was found to be upregulated only in tumor ECs of highly metastatic tumors." (PMID 34073394, 2021). "As each human tumor creates its own unique microenvironment, assessment of BGN expression represents a promising approach for identifying patients with the greatest potential to benefit from immunotherapy and a new venture into personalized therapy for cancer patients." (PMID 35096572, 2021). "We then investigated biglycan expression in the mouse E0771 tumor model." (PMID 33966638, 2021). "A wide variety of mechanisms have been implicated in biglycan-mediated tumor progression, including upregulation of VEGF, the binding of biglycan to toll-like receptors, or by modulation of signaling pathways including the canonical Wnt pathway and the NF-κB pathway." (PMID 35008869, 2021). "Blockage of the Bgn-TLR2 or Bgn-TLR4 interaction in E0771 cells by neutralizing antibodies significantly decreased Tnf mRNA expression in E0771 cells stimulated with recombinant biglycan, suggesting that biglycan regulates TNF-ɑ expression in tumor cells through binding to TLR2 and TLR4." (PMID 33966638, 2021). "Notably, BGN expression levels were also observed to be strongly correlated with tumor size and serosa invasion in our sample set." (PMID 35096572, 2021).
tumor (continued). "Tumor suppressive effects have, for instance, been reported in pancreatic cancer cell lines, where treatment with exogenous biglycan leads to an up-regulation of cyclin-dependent kinase inhibitor p27, down-regulation of Cyclin A and PCNA (proliferating cell nuclear antigen), and cell cycle arrest." (PMID 34917515, 2021). "A total of 84 patients (58.3%) stained positive for BGN expression in tumor tissues." (PMID 35096572, 2021). "Importantly, when comparing paired-wise tumor and normal samples from the same patients, we observed an up-regulation of BGN expression levels in all studied patients." (PMID 33809543, 2021). "Moreover, the use of additional in vivo models to study tumor growth, as mice models, should also carried out to determine the effect of biglycan expression in a longer experiment." (PMID 33809543, 2021). "BGN may display versatile and complex roles in the tumor immune response, which may depend on the cellular context according to previous reports and our study." (PMID 35096572, 2021). "Furthermore, biglycan expression was higher in the tumor stromal compartment compared to the epithelial compartment." (PMID 33966638, 2021). "Similarly, univariate analysis revealed that sex, tumor marker, SCC, histology, T factor, and BGN expression were significantly associated with overall survival." (PMID 33709550, 2021). "Biglycan has been reported to be expressed in the tumor microenvironment." (PMID 33966638, 2021). "Interestingly, biglycan is a homolog of decorin, but seems to have tumor promoting capacities by angiogenesis induction in contrast to decorin." (PMID 32984308, 2020). "Biglycan and endocan are important proteoglycans in angiogenesis and thus tumor progression." (PMID 32984308, 2020). "Indeed, elevated biglycan levels induced higher density of blood vessels and increased tumor growth in vivo of colorectal cancer xenografts via induction of VEGF expression." (PMID 32984308, 2020). "In case of biglycan, strong tumor and stromal immunoreactivity was observed." (PMID 32984024, 2020). "We have shown that biglycan, a small leucine-rich repeat proteoglycan, was remarkably upregulated in TECs and facilitated the migration of toll-like receptor-expressing tumor cells, which increased circulating tumor cells and lung metastasis." (PMID 31600937, 2019). "Furthermore, our result shows that BGN (Biglycan) is highly expressed in CSCs, and BGN has been reported to promote tumor invasiveness via inducing integrin-β1 expression." (PMID 31118022, 2019). "In addition, patients with high BGN levels were associated with significantly worse DFS than those with low expression, suggesting that higher expression of BGN indicates invasive tumor behavior and predicts poor clinical outcome in ESCC patients." (PMID 31950035, 2019). "Thus, these developments indicate that biglycan signaling can bridge innate and adaptive immunity, with the ability to act at different check points of the tumor immune cycle." (PMID 31068944, 2019). "In the present study, we have found a novel role of celastrol as an anti-tumor medicine through reducing the expression of BGN to activate RIP1/RIP3/MLKL signaling pathway, leading to necroptosis and decreased secretion of pro-inflammatory cytokines in HGC-27 and AGS cells." (PMID 31739592, 2019). "Indeed, TEC biglycan facilitated the migration of toll-like receptor-expressing tumor cells through the activation of nuclear factor-kappa B (NF-κB) and extracellular signal-regulated kinase (ERK) signaling." (PMID 29695087, 2018). "GC cells secrete BGN into the tumor stroma and promote GC progression." (PMID 29484116, 2018). "For example, recombinant biglycan from Chinese hamster ovary cells was used in this study, but its conjugation with chondroitin sulfate or dermatan sulfate might be evaluated to further understand biglycan’s action on tumor cells." (PMID 29615735, 2018).
tumor (continued). "Mass spectrometry-based analysis predicted that several bone matrix proteins (e.g., collagen, biglycan) in conditioned medium could be responsible for tumor shrinkage." (PMID 29615735, 2018). "Biglycan from tumor endothelial cells stimulates the tumor cells to metastasize." (PMID 28763139, 2017). "Interestingly, its close structural relative, biglycan, has been shown to possess opposite function, namely tumour-promoting activity." (PMID 28653173, 2017). "Thus, we cultured LM-TECs in CM derived from HM-tumour cells, LM-tumour cells, or LM-TECs (Control) for 2 days, after which biglycan mRNA expression was evaluated." (PMID 27295191, 2016). "Tumour cell migration toward biglycan was inhibited by the NF-κB inhibitor BAY11-7082." (PMID 27295191, 2016). "Since there were no additive effects by inhibition of both TLR2 and TLR4, it was suggested that one of these TLRs may be sufficient for tumour cells to utilize biglycan." (PMID 27295191, 2016). "Moreover, the MVD of tumours co-implanted with shBiglycan HM-TECs decreased, which suggests that biglycan from the ECs induced tumour angiogenesis." (PMID 27295191, 2016). "Furthermore, strong biglycan expression was observed in HM-tumour vessels, but was hardly observed in LM-tumour vessels or in normal skin vessels." (PMID 27295191, 2016). "Tumour cell intravasation was enhanced by TEC-derived biglycan and vice versa." (PMID 27295191, 2016). "In support of this view, the tumour cells utilized in this study expressed TLR2 and TLR4, and neutralizing antibodies against these receptors indeed inhibited tumour cell migration toward biglycan, which suggested a common mechanism for biglycan to activate cell migration." (PMID 27295191, 2016). "Biglycan mRNA in LM-TECs was upregulated after treatment with HM-tumour-CM and the number of migrating LM-tumour cells increased when HM-tumour CM-treated LM-TECs were plated in the lower chambers of transwells." (PMID 27295191, 2016). "In our study, macrophages may be mobilized by TEC-derived biglycan and this may contribute to tumour metastasis." (PMID 27295191, 2016). "Co-implantation of control HM-TECs with LM-tumours resulted in increased plasma biglycan levels." (PMID 27295191, 2016). "Thus, our observations and those of Schedin and colleagues do not agree with the conclusion of Bischof and colleagues that biglycan is sufficient for tumor cell normalization and that tumor cell normalization is unique to inductive mesenchyme." (PMID 25927296, 2014). "BGN staining intensity increased in muscle-invasive tumor stages." (PMID 24223213, 2013). "Therefore, the role of BGN in tumor progression likely depends on the tumor type, stage and differentiation." (PMID 24223213, 2013). "This hypothesis is particularly interesting because BGN is expressed in high amounts by tumor and stromal cells and is relatively stable in contrast to ATP, the principle ligand of all purinergic receptors." (PMID 24223213, 2013). "In addition, a correlation of the BGN positive area fraction and invasiveness of the tumor was detected (p=0.0025)." (PMID 24223213, 2013). "For the first time, we demonstrated that biglycan might be a novel marker of TECs and is activated during tumour angiogenesis." (PMID 22374465, 2012). "It was suggested that biglycan is expressed specifically in tumour blood vessels." (PMID 22374465, 2012). "Furthermore, immunostaining revealed strong biglycan expression in vivo in human tumour vessels, as in mouse TECs." (PMID 22374465, 2012). "Finally, CD44, CD166, CD29, CEACAM5, cadherin 17, and biglycan were identified by mass spectrometry to be enriched in CD133+ tumour spheroid cells." (PMID 20332776, 2010). "Altogether, these data indicate that biglycan acts as a molecular regulator with dual and context-dependent functions in BC: while its stromal and endothelial expression promotes angiogenesis, immune evasion, and metastatic relapse, its absence appears to restrain tumour progression." (PMID 41463344, 2025).